AR (androgen receptor)
Diseases named in the same sentence as AR in open-access papers (continued):
Sharing a sentence is not in itself a finding about the gene and the disease.
prostate carcinoma (continued). "In addition to antagonizing AR signaling, polyamide 1 is also cytotoxic towards prostate cancer cells." (PMID 26571387, 2015). "Also prostate cancer cells devoid of AR were transfected with human AR and showed a decreased proliferation rate." (PMID 26715186, 2015). "Other examples include androgen receptor (AR) in prostate cancer, and MITF in melanoma." (PMID 26556242, 2015). "Similarly, our data in this study show inhibition of AR by Enzalutamide dramatically blocked prostate cancer cells entering S phase from G1, especially in androgen-dependent LNCaP cells." (PMID 26506516, 2015). "Importantly, there is a paucity of studies of androgen manipulation in AR+ tumors other than prostate cancer." (PMID 25595907, 2015). "Interestingly, several other catalytic inhibitors of Topo II including Merbarone, Aclacinomycin A and Genistein all showed suppressive impacts to AR signaling in prostate cancer cells." (PMID 26009876, 2015). "Hence, we wanted to further analyze the effect of 5-Lox inhibition on the LNCaP human prostate cancer cell-derived C4-2B cells which still retain the androgen receptor, but are refractory to androgen stimulation." (PMID 25875826, 2015). "Here we show, in the PTEN-deficient model of prostate cancer, that the expression of ERα (but not AR or ERβ) is significantly increased in regions of tumors where cell proliferation is notably enhanced." (PMID 25436982, 2015). "Further studies have shown that GRβ may also enhance androgen receptor (AR) induced growth in prostate cancer cells." (PMID 26347776, 2015). "The study suggested that prostate cancer patients with androgen receptor positive tumors might specifically benefit from (−)-epicatechin and its analogs as therapy enhancing drugs." (PMID 26180580, 2015). "In summary, using integrative genomics of FAIRE-seq, AR ChIP-seq, publically available transcriptomic data and patient survival data, we successfully determined a minimal gene signature for the outcome of patients with prostate cancer." (PMID 26412853, 2015). "Moreover, it has been commonly agreed that AR expression and signaling remains intact as the disease evolves from androgen-sensitive cancer to castration-resistant prostate cancer (CRPC) which are still dependent on AR signaling axis." (PMID 25852559, 2015). "Interestingly, AR/p52-02 was also previously found to inhibit the interaction between AR and JunD in our study on an ROS generation pathway in prostate cancer cells." (PMID 26622945, 2015). "Interestingly, these genes were found to be different from those regulated by the androgen receptor, the main target for prostate cancer treatment." (PMID 25933120, 2015). "However, an early event that is common among prostate cancers is a transition from AR-mediated growth suppression and differentiation of luminal epithelial cells to AR-mediated growth and proliferation of malignant versions of these cells." (PMID 26372468, 2015). "Although the etiology of prostate cancer remains speculative, androgen receptor signaling is confirmed to play a pivotal role in development and progression." (PMID 26154658, 2015). "In addition to well-described roles in plant growth, EBR induces apoptosis in the LNCaP prostate cancer cells expressing functional androgen receptor (AR)." (PMID 26353013, 2015). "In addition, stable expression of AR in PC-3 prostate cancer cells profoundly suppressed cell proliferation and tumor growth in intact-male mouse xenografts." (PMID 26372468, 2015). "Androgen receptor pathway antagonism is one of the major strategies in prostate cancer therapy." (PMID 26196320, 2015). "Previously we showed AAE exerted its anti-cancer effect in several prostate cancer cell lines in vitro and LNCaP tumors in vivo, and identified a compound with anti-proliferative and anti-androgen receptor functions: Ericifolin, [Eugenol 5-O-β-(6′-galloylglucopyranoside)], from AAE." (PMID 25945840, 2015).
prostate carcinoma (continued). "We also confirmed RUNX1 induction by androgen in other AR positive prostate cancer cells." (PMID 25537508, 2015). "Hence, it can be deduced that a decrease in LMTK2 expression observed in prostate cancer patient promotes tumor cells proliferation by enhancing AR transcriptional activity." (PMID 26008968, 2015). "According to a previous report, pentagalloyl glucose suppressed rat liver microsomal 5α-reductase activity and expression of the androgen receptor in prostate cells, resulting in a significant reduction in androgen-induced prostate cancer cell growth and fatty acid synthase by pentagalloyl glucose." (PMID 25709710, 2015). "Furthermore, FTY720 has been reported to be a sphingosine kinase 1 inhibitor that reduces the expression of androgen receptor in prostate cancer cells." (PMID 26023836, 2015). "When we checked the ERα, ERβ and AR status in different prostate cancer cells as well as in a benign prostatic hyperplasia cell line (BPH-1), we detected ERα protein in some prostate cancer cells and ERβ protein in all cell lines even though ERα mRNA was detected in all the cells tested." (PMID 26575018, 2015). "The expression of miR-101 was found to correlate with AR status in prostate cancer cell lines." (PMID 26473737, 2015). "In chondrosarcoma, a decrease in HDAC4 expression leads to the upregulation of vascular endothelial growth factor expression, thereby stimulating angiogenesis; in prostate cancer cells, HDAC4 downregulation was associated with a high level of androgen receptor expression, which promoted cell growth." (PMID 25557107, 2015). "MiR-101 expression correlated with AR status in prostate cancer cell lines." (PMID 26473737, 2015). "It appears from our results and those of others that stromal AR may also promote prostate cancer proliferation, as suggested here by the production of an unidentified soluble mediator, and/or ECM-bound growth factor." (PMID 25965833, 2015). "We hypothesized that AR contributes to prostate cancer cell migration and invasion, possibly through stimulation of integrin α6β1 transcription." (PMID 25730905, 2015). "Androgen receptor (AR) signaling is a key pathway modulating prostate cancer (PCa) progression." (PMID 25789054, 2015). "Overall, the data suggest that specifically inhibiting the interaction of AR with p52 and blocking activity of p52 and pARser81 may be an effective means of reducing castration-resistant prostate cancer cell growth." (PMID 26622945, 2015). "Indeed, ligand-bound AR decreases the transcriptional activity of TCF4 in prostate cancer, colon cancer, and neurons." (PMID 26207810, 2015). "Differential expression levels of AR pioneer factors and coregulators correlate with clinical outcome, implicating deregulation of the androgen-signaling axis in prostate cancer development and progression." (PMID 26412853, 2015). "The evidence of reciprocal regulation of c-Myc and AR expression, co-expression in castration-resistant prostate cancer, and ligand-independent AR activation by c-Myc may explain the genomic instability or metabolic changes observed in prostate cancer." (PMID 26318424, 2015). "Importantly, these N-terminal domain antagonists have been shown to retain activity in prostate cancer cell lines expressing AR-Vs." (PMID 26566796, 2015). "For these reasons, androgen deprivation therapy (ADT) is an effective treatment in prostate cancer, although most patients progress to castration-resistant prostate cancer with an increase of AR expression levels and hypersensitivity to androgen-based therapies." (PMID 25693204, 2015). "So, it was suggested that targeting AR or related cell signaling pathways could inhibit prostate cancer S/P cells proliferation, which could be a new strategy to treat castration resistant prostate cancer (CRPC)." (PMID 25943311, 2015).
prostate carcinoma (continued). "Furthermore, LMTK2 immunostaining and duolink data in this report indicates a nuclear translocation of LMTK2/AR complexes in response to androgen treatment of prostate cancer cells." (PMID 26008968, 2015). "One could consider castration the first molecularly targeted therapy in oncology, reducing activity of AR, which drives prostate cancer growth and proliferation." (PMID 26258074, 2015). "Indeed, most prostate cancers express AR, are androgen-dependent for their growth and, as a result of androgen withdrawal, can undergo either cell cycle arrest or even apoptosis." (PMID 25693204, 2015). "Previous reports have suggested that sorafenib could inhibit prostate cancer cell survival by decreasing proliferation and inducing apoptosis through the downregulating of AR." (PMID 25953027, 2015). "To date, no AR variants have been reported from the primary organ of a preclinical mouse model of prostate cancer." (PMID 26196517, 2015). "Future studies aimed at defining the precise mechanism of PABPC1 regulation of AR signaling may lead to new approaches to prevent and/or treat prostate cancer patients." (PMID 26176602, 2015). "Knockdown of AR in AR-positive prostate cancer cells resulted in enhanced autophagy." (PMID 26473737, 2015). "Androgen ablation, through suppression of androgen biosynthesis and/or antagonism of AR activity, initially induces apoptosis in a subset of prostate cancer cells and suppresses growth and proliferation in those that survive, which is evidenced by tumor regression and subsequent regrowth." (PMID 26372468, 2015). "Activation of androgen receptor (AR) is crucial for prostate cancer growth." (PMID 26137992, 2015). "Human prostate cancer tissues obtained from four patients with moderate (Gleason 7) tumors were combined as heterotypic recombinants with AR positive human prostate PShTert-AR myofibroblasts or AR negative PShTert-ctrl and sub-renally grafted into immunodeficient NOD-SCID mice." (PMID 25965833, 2015). "In addition, ODM-201 reduces the growth of AR-overexpressing VCaP prostate cancer cells both in vitro and in a castration-resistant VCaP xenograft model." (PMID 26137992, 2015). "PSAP has been previously reported to induce AR protein in prostate cancer cells." (PMID 26341737, 2015). "The combined effect of cell cycle deregulation via RB1 and E2F1 and of AR re-activation was hypothesized to promote prostate cancer progression to castration resistance." (PMID 25575823, 2015). "Interestingly, similar to ACK1, Src is also known to interact and modify AR to modulate expression of the AR target genes in prostate cancer cell lines." (PMID 26546517, 2015). "Thus, MJC13 can inhibit basal, DHT and β-catenin stimulated proliferation in this AR-dependent prostate cancer cell line and MJC13 actions differ from those of flutamide or bicalutamide." (PMID 26332122, 2015). "Androgen receptor signaling pathway plays an important role in prostate cancer progression." (PMID 25860954, 2015). "In contrast, knock down of LMTK2 in HEK293 cells expressing AR (analogous to prostate cancer cells) enhanced androgen-dependent activation of reporter gene by three fold in comparison to parental cells and by six fold in comparison to cells overexpressing LMTK2." (PMID 26008968, 2015). "Splice variants of AR lacking the ligand-binding domain have been found to be expressed in prostate cancer cells." (PMID 25950519, 2015). "AR/p52-02 also caused a reduction in levels of p21WAF/CIP1, which is a direct AR targeted gene in that its expression correlates with androgen stimulation and mitogenic proliferation in prostate cancer under physiologic levels of androgen, likely by disrupting the AR signaling axis." (PMID 26622945, 2015). "Curcumin analogues efficiently inhibited AR activity in prostate cancer cells." (PMID 25705125, 2015).
prostate carcinoma (continued). "Based on these results, we speculate that RUNX1 may be essential for the survival of prostate cancer cells as AR is the key signal factor in clinical prostate cancer progression." (PMID 25537508, 2015). "While the functional role of HES5 methylation in prostate tumourigenesis is yet to be determined, we found that demethylation resulted in downregulation of the HES5-target gene HES6, which has recently been shown to drive progression in prostate cancer via the androgen receptor." (PMID 25560400, 2015). "The knowledge that Topo II is required for AR transcriptional activity may lead to two possible therapeutic strategies for prostate cancer patients." (PMID 26009876, 2015). "The molecular mechanisms by which curcumin inhibited growth of androgen-dependent and -independent prostate cancer cells were reported in other studies demonstrating that pathways and transcription factors other than AR-mediated and -regulated downstream genes were involved in this process." (PMID 25971429, 2015). "The antitumor action of MLT in prostate cancer cell lines has been attributed to changes in cell cycle, androgen receptor (AR) translocation, and inhibition of angiogenesis through reduced expression of factors that act under hypoxic conditions, such as hypoxia-inducible factor 1α (HIF-1α)." (PMID 26295055, 2015). "Similarly, expression of active Notch was found to downregulate AR activity in prostate cancer cells." (PMID 25592291, 2015). "Deregulation of androgen/AR signaling perturbs the normal development of reproductive tract and accounts for a wide range of pathological conditions such as androgen-insensitive syndrome and prostate cancer." (PMID 25693204, 2015). "Interestingly, NEDD4 has been shown to negatively regulate the stability of AR in prostate cancer cells." (PMID 25823820, 2015). "If those agents can improve prognosis, head-to-head comparison between up-front chemotherapy and up-front novel AR-targeting agents would be warranted in future, which could lead to major changes in prostate cancer therapy." (PMID 26793621, 2015). "In addition, Chen previously found that baicalein can regulate the expression of the androgen receptor, inhibit the proliferation of prostate cancer cells, and induce the apoptosis of these cells." (PMID 25957503, 2015). "Indeed, ELK1-shRNA modestly increased the cell growth of AR-positive prostate cancer as well as bladder cancer in androgen-depleted conditions." (PMID 26342199, 2015). "Notably, UXT is highly expressed in various tumor tissues, and serves as a co-activator of androgen receptor in prostate cancer." (PMID 25617435, 2015). "Also, blocking AR activation by a small molecule that binds to the N-terminal domain (NTD) can inhibit castration-resistant prostate cancer cell growth." (PMID 26622945, 2015). "Prostate cancer cells rely on AR in all stages of growth and progression." (PMID 26622945, 2015). "By manipulating AR activity in several different prostate cancer cell lines through RNAi, drug treatment, and the use of a nuclear-deficient AR mutant, we demonstrate that androgen acting on cytoplasmic AR rapidly stimulates Src tyrosine kinase via a non-genomic mechanism." (PMID 25730905, 2015). "Furthermore, we have previously reported that insulin and insulin-like growth factor–1 (IGF–1) accelerate prostate cancer cell proliferation through androgen receptor (AR) activation by disrupting its direct interaction with Foxo1." (PMID 26439622, 2015). "It has been reported that AZD5363, an AKT inhibitor potently inhibited proliferation and induced apoptosis in prostate cancer cell lines expressing the AR and had anticancer activity in vivo in androgen-sensitive and castration-resistant phases of a LNCaP xenograft model." (PMID 26506516, 2015). "MiR-190a contributes the human prostate cancer cell growth through AR-dependent signaling." (PMID 26314494, 2015).
prostate carcinoma (continued). "This developmental pathway may become active in prostate cancer where p110β and AR have previously been reported to functionally interact." (PMID 26132308, 2015). "Together, these findings led us to hypothesize that catalytic Topo II inhibitors may block AR signaling and induce G2/M cell cycle arrest in prostate cancer cells." (PMID 26009876, 2015). "Most important, we show that dual inhibition of AR and PI3K/mTOR signaling pathways has synergistic inhibitory effect of cell growth associated with increase of apoptosis in both castration-sensitive and resistant prostate cancer cells." (PMID 26506516, 2015). "It has been reported that AR plays an important role in therapeutic resistance in prostate cancer." (PMID 25781993, 2015). "Based on these studies, we hypothesize that inhibiting the interaction of AR and p52 may prevent the castration-resistant growth and enzalutamide resistance of prostate cancer cells." (PMID 26622945, 2015). "The significant reduction of nuclear pARser81 level under low androgen condition in both LNCaP and C4-2 by AR/p52-02 at growth inhibitory concentrations further supports that phosphorylation of AR at ser81 is important for growth of prostate cancer cells under low androgen condition." (PMID 26622945, 2015). "The current research and our work showed that AR expression was low in prostate cancer S/P cells." (PMID 25943311, 2015). "Indeed, ER- and androgen receptor (AR)-induced transcription in breast and prostate cancer involves transient DSBs generated by TOP1 and TOP2." (PMID 26411678, 2015). "Androgen receptor (AR) is the key indicator for prostate cancer prognosis." (PMID 25885018, 2015). "AR is relatively well-known for its oncogenic role, especially in prostatic carcinomas." (PMID 26249023, 2015). "Prostate cancer (PCa) development and progression is driven by the androgen receptor (AR)." (PMID 26452038, 2015). "Curcumin analogues may facilitate degradation of androgen receptor (AR) in prostate cancer, and may induce apoptosis of prostate cancer cell by IkBalpha, c-Jun and androgen receptor." (PMID 26490686, 2015). "For example, E006AA and PC-3 prostate cancer cells display a complete absence of AR growth-regulatory function due to loss of AR-dependent growth suppression." (PMID 26372468, 2015). "As both KLK3 and KLK2 genes are regulated by AR signalling, it is reasonable to theorize that the 11B6 antibody could be used to image AR signalling in prostate cancer in a similar fashion to that reported with 5A10." (PMID 26116115, 2014). "In addition, we searched the microarray data in the public domains for effects of androgens on CAMK2N1 mRNA expression in AR-positive prostate cancer cell lines, and similar observation was also made in this database." (PMID 25296973, 2014). "We examined three cell lines: LNCaP cells are responsive to 5-alpha-dihydrotestosterone (DHT), which means they contain a functioning androgen receptor (AR) and are indicative of an early stage prostate cancer cell line even though they are metastatic in nature." (PMID 25400509, 2014). "As CDK11p58 could inhibit the transcription activity of AR, we speculated CDK11p58 could inhibit the metastasis of prostate cancer through AR signaling." (PMID 24397471, 2014). "As our toolbox for targeting AR function expands, our ability to evaluate AR expression and function within tumor samples from patients with late-stage disease will likely be a critical component of the personalized management of advanced prostate cancer." (PMID 25424879, 2014). "AR is involved in the metastasis and invasiveness of prostate cancer." (PMID 24397471, 2014). "Previous studies have reported the role of AR in the regulation of apoptosis in prostate cancer." (PMID 24658443, 2014). "Reciprocal activation of AR and PI3K/AKT signaling in prostate cancers could complicate the outcome of PCa patients receiving combinational treatments of AR and PI3K/AKT inhibition." (PMID 25360799, 2014).